MMP9 (matrix metallopeptidase 9)
Diseases named in the same sentence as MMP9 in open-access papers (continued):
Sharing a sentence is not in itself a finding about the gene and the disease.
diabetic foot ulcers (21 papers, 2012 to 2025). "Elevated levels of MMP-9 have been associated with poorer wound outcomes, particularly in diabetic foot ulcers and venous ulcers." (PMID 39408801, 2024). "High expression of MMP-9 is reportedly associated with protein tyrosine phosphatase-1B in skin, and aberrant serum growth factor levels prevent healing of diabetic foot ulcers." (PMID 25884474, 2015). "A study conducted on diabetic patients with diabetic foot ulcers shows that elevated serum levels of MMP-9 and the MMP-9/TIMP-1 ratio are associated with poor wound healing." (PMID 40243433, 2025). "Studies report wound fluid levels of MMP9 at initial presentation in the clinic as an important predictor of the healing outcomes in diabetic foot ulcers." (PMID 36839533, 2023). "AGEs induced the demethylation of the MMP-9 promoter through the downregulation of GADD45a, which is involved in diabetic foot ulcers." (PMID 36866277, 2023). "It was reported previously that MMP1, MMP2 and MMP9 are significantly over-expressed in diabetic fibroblasts and are important determinants of diabetic foot ulceration morbidity and exacerbation." (PMID 28423369, 2017). "For instance, high concentrations of MMP-9 and high MMP-9 : tissue inhibitors of MMP (TIMP-1) ratio in wound fluid predict poor wound healing in diabetic foot ulcers." (PMID 26356299, 2015). "In recent years, domestic and international studies have found that increased matrix metalloproteinases (MMPs) expression would contribute to the vulnerability of diabetic skin and the refractory nature of diabetic foot ulcers, especially MMP9." (PMID 22577368, 2012). "The findings suggested that MMP9 deters the healing of diabetic foot ulcers by inhibiting the biological behaviors of fibroblasts." (PMID 22577368, 2012). "Studies suggest that activating ERK1/2 could increase MMP9 (matrix metalloproteinase 9) expression, leading to delayed wound healing in conditions like diabetic foot ulcers." (PMID 39329977, 2024). "It is widely recognized that high levels of MMP9 slow down the healing of diabetic foot ulcers by excessive degradation of extracellular matrix, growth factors, growth factor receptors, integrins, and their receptors, as well as increasing the local inflammatory response in the wound." (PMID 22577368, 2012). "The rs3918242 SNP affects the promoter region of the MMP-9 and has been implicated in increasing risk for myocardial infarction, lower ejection fraction, progression to left ventricular systolic abnormalities, multiple gingival recessions, ischemic stroke, T2DM, and diabetic foot ulcers." (PMID 39408801, 2024). "Mechanisms could include the dampening of the pathologically excessive levels of collagenases (MMP-1 and MMP-8) and gelatinases (MMP-2 and MMP-9) that have been observed in biopsies of diabetic foot ulcers, compared to the levels of these proteinases seen in normal posttraumatic wounds." (PMID 27190999, 2016).
meningitis (21 papers, 2004 to 2025). A disorder characterized by acute inflammation of the meninges of the brain and/or spinal cord. "Patients with meningoencephalitis seem to have significantly higher single nucleotide polymorphism in the MMP-9 gene, rs 17576, than patients with meningitis." (PMID 39860968, 2024). "Given that one of the most important pathologies caused by S. suis in diseased pigs is meningitis, MMP-9 could play an important role in the infection." (PMID 30373658, 2018). "This contribution of S. suis DNase in cytokine and MMP-9 secretion may be of utmost importance in the pathogenic process of meningitis." (PMID 24996230, 2014). "Also, CSF samples from patients who had meningitis caused by infectious agents other than Brucella spp., exhibited MMP-9 activity." (PMID 23587438, 2013). "Moreover, ZmpC promotes the expression of inflammatory factors and cleaves human MMP-9, suggesting that ZmpC may be a key factor in the meningitis caused by S. suis Chz type CZ130302." (PMID 39080654, 2024). "In a rat model of meningitis, the transcriptional level of MMP-9 in brain tissue was significantly increased." (PMID 39080654, 2024). "Of note, MMP-9 activity was also present in CSF of patients suffering from meningitis due to other bacteria which are known to produce the same parenchymal inflammation of brain and spinal cord (encephalomyelitis) as that observed in neurobrucellosis." (PMID 23587438, 2013). "We and others have shown that CSF concentrations of MMP-9 are elevated in all forms of meningitis and CSF MMP-9 concentrations (corrected for CSF white cell count) were significantly associated with fatal TBM and the extent of cerebral tissue damage." (PMID 19789647, 2009). "Differences in the activity of MMP-9 (assessed by zymography) have been reported in experimental pyogenic meningitis where treatment with antibiotics alone increased CSF MMP-9 activity, but dexamethasone co-administration suppressed this effect." (PMID 19789647, 2009). "MMP-9 produced by leukocytes during meningitis is essential to enable them to migrate through the BBB." (PMID 19603075, 2009). "It is also established that most of the resident cells in human brain have the capacity to produce MMP-2 and MMP-9 – enzymes that are known to participate in brain damage (e.g. in case of infectious meningitis)." (PMID 15535833, 2004). "Cleavage of MMP-9 by ZmpC in S. suis Chz type strain CZ130302 may play an important role in the development of meningitis." (PMID 39080654, 2024). "In this study, ZmpC-mediated cleavage in S. suis CZ130302 may also activate MMP-9, thereby promoting the development of meningitis." (PMID 39080654, 2024). "In addition, MMP-9 was found to contribute to brain damage associated with N. meningitides meningitis significantly, and inhibition of MMP-9 reduced intracranial complications in mice suffering from N. meningitides meningitis." (PMID 36769171, 2023). "In addition, increased BBB permeability by MMP-9 plays a pivotal role in infectious encephalitis and meningitis." (PMID 36142454, 2022). "Moreover, high concentrations of MMP-9 are observed in vivo in the cerebrospinal fluid during bacterial meningitis and in an experimental model of meningitis." (PMID 24996230, 2014). "Adjunctive treatment with dexamethasone is associated with an inflammatory process reduction in the subarachnoid space; it decreased the caspase-3 activation, inhibited the MMP-9 expression in the rat brains inoculated with S. pneumoniae, and improved neurologic outcomes in meningitis." (PMID 22191010, 2011). "To further explore the role of ZmpC in the development of meningitis, we determined the transcript levels of TNF-α, IL-8, and MMP-9 in the brain tissue of mice infected with CZ130302 and ΔzmpC." (PMID 39080654, 2024).
meningitis (continued). "Encephalitis and meningitis patients differed with respect to other chemokines (CXCL11) and MMPs (MMP-3, MMP-8, MMP-9, and MMP-12), indicating that different location of the virus gives rise to qualitative differences in the ensuing inflammatory response." (PMID 30777092, 2019). "Serum levels of MMP-9 were significantly increased in encephalitis, meningitis, and Ramsay Hunt syndrome patients whereas serum MMP-3 levels were higher in meningitis and Ramsay Hunt syndrome compared to controls." (PMID 30777092, 2019).
pituitary adenomas (21 papers, 2011 to 2025). "Additionally, TNF-α administration caused hemorrhagic transformation and enhanced VEGF and MMP-9 expression in MMQ pituitary adenoma cell xenografts in mice." (PMID 21747731, 2011). "Recent evidence indicates that CD44, CD34, PTTG, FGFR4, MMP9, E‐Cadherin, and N‐Cadherin serve as biomarkers of aggressive pituitary adenomas." (PMID 41017273, 2025). "SPD304, as a small‐molecule inhibitor of TNFα, can inhibit the upregulation of TNFα on MAPK and MMP9, thereby reducing the membrane invasion capability and bone invasion ability of pituitary adenoma cells." (PMID 38739004, 2024). "MMP‐9 is the first matrix metalloproteinase found to be significantly upregulated in pituitary adenomas infiltrating the cavernous sinus, and subsequent studies have further confirmed its crucial role in the invasion of pituitary adenomas." (PMID 38739004, 2024). "Studies in patients with invasive pituitary adenomas showed a significantly higher MMP-9 expression when compared to non-invasive pituitary adenomas." (PMID 37206663, 2023). "Matrix metalloproteinase family members, primarily MMP-2 and MMP-9, have been well-recognized as core molecules responsible for the invasion of pituitary adenomas by our previous studied and other studies." (PMID 35463323, 2022). "The correlation between MMP-9 overexpression and invasiveness of pituitary adenomas has been verified by many researchers in human pituitary adenoma specimens as well as cell lines." (PMID 30733705, 2019). "MMP-9 is the first matrix metalloproteinase found to have a significantly higher expression level in pituitary adenomas invaded to cavernous sinus." (PMID 30733705, 2019). "Interestingly, IL6R signaling through the JAK2/STAT3/MMP9 axis was previously reported to promote the invasion of pituitary adenoma cells." (PMID 40002253, 2025). "MMP‐9 overexpression correlates with higher invasive grades in human pituitary adenomas." (PMID 41017273, 2025). "The study pointed out that hypoxia-inducible factor-1α, pituitary tumor transforming gene, vascular endothelial growth factor, fibroblast growth factor-2, and matrix metalloproteinases (MMPs, mainly MMP-2, and MMP-9) are core molecules responsible for the invasiveness of pituitary adenomas." (PMID 30733705, 2019). "MMP-9 plays an important role in promoting invasiveness in many type of pituitary adenomas." (PMID 30733705, 2019). "Moreover, high levels of MMP-9 are observed in hemorrhagic pituitary adenomas, thereby suggesting a possible role of MMP-9 in the development of hemorrhage within the pituitary adenomas." (PMID 29615979, 2018). "MMP-9 mRNA expression analysis in pituitary adenomas was performed." (PMID 28194042, 2017). "MMP-9 expression was reported to be significantly higher in invasive pituitary adenomas." (PMID 28194042, 2017). "In bone-invasive pituitary adenomas, TNFα activates the MAPK pathway autocrinely and promotes MMP9 expression, further accelerating membrane invasion." (PMID 40351428, 2025). "Multiple studies have demonstrated significantly higher expression of MMP-9 and/or MMP-2, among others, in invasive pituitary adenoma compared to non-invasive tumors." (PMID 41206839, 2025). "The excessive TNFα acts on pituitary adenoma cells in an autocrine manner, activating the MAPK signaling pathway and increasing the expression of MMP9." (PMID 38739004, 2024). "Bone‐invasive pituitary adenoma secretes higher levels of TNF‐α, which then acts on itself in an autocrine manner, activating the MAPK pathway and promoting the expression of MMP9, thereby accelerating the membrane invasion process." (PMID 38739004, 2024). "The major types of MMPs involved in pituitary adenoma invasion can be classified into collagenases (MMP-1), gelatinases (MMP-2 and MMP-9), stromelysins (MMP-3), and membrane type (MMP-14) according to their function and location." (PMID 30733705, 2019).
pituitary adenomas (continued). "The objective of this meta-analysis was to assess the relationship between expression of MMP-9, MMP-2, and TIMP-2 and invasion of pituitary adenomas." (PMID 27310993, 2016). "Taken together, our results show that TNF-α significantly correlates with intratumoral hemorrhage in pituitary adenomas and induces pituitary adenoma hemorrhage through up-regulation of VEGF and MMP-9." (PMID 21747731, 2011). "Importantly, the knockdown of β-Catenin inhibited pituitary adenoma cell proliferation and migration probably by inhibiting AKT, STAT3, Cyclin D1, CDK4, MMP-2, and MMP-9." (PMID 35928898, 2022). "Similarly, 5 μM Rottlerin (Calbiochem) had been previously found to markedly inhibit both FGF2- and TPA-induced MMP-9 secretion in MCF-7 cells as well as basal and PMA-induced MMP-9 expression in pituitary adenoma cells." (PMID 22272173, 2012). "We evaluated TNF-α, VEGF and MMP-9 expression in surgical specimens of hemorrhagic and non-hemorrhagic pituitary adenomas." (PMID 21747731, 2011). "Exposure of MMQ pituitary adenoma cells to TNF-α induced VEGF and MMP-9 expression in vitro." (PMID 21747731, 2011). "This study suggests that TNF-α may play a role in the development of intratumoral hemorrhage in pituitary adenomas via up-regulation of VEGF and MMP-9." (PMID 21747731, 2011). "Moreover, elevated expression of MMP-9 is observed in haemorrhagic pituitary adenomas as compared to non-haemorrhagic tumors." (PMID 29615979, 2018). "The results indicated that MMP-9 and -2 may be correlated with invasiveness of pituitary adenomas, although their relationship with functional status of pituitary adenomas is still not clear." (PMID 27310993, 2016). "Moreover, hemorrhagic pituitary adenomas exhibit higher MMP-9 protein expression levels than non-hemorrhagic tumors." (PMID 21747731, 2011). "However, no statistical difference in the MMP-9 expression level between invasive and non-invasive non-functioning pituitary adenomas could be found." (PMID 30733705, 2019). "This retrospective cohort study aimed to study the expression of tumoral biomarkers (CTSK, MMP9, MMP2, TIMP2, and PTTG1) and evaluate their clinical significance in non-functioning pituitary adenomas (NFPAs) with different invasion patterns." (PMID 36052250, 2022). "A transcriptome and proteome analyses on pituitary null cell adenomas, a subtype of non-functioning pituitary adenomas, by the same research team, identified that upregulated IL-6R/JAK2/STAT3 promoted invasiveness via MMP-9." (PMID 30733705, 2019). "In human pituitary adenoma surgical specimens, higher expression levels of TNF-α, VEGF, and MMP-9 were found in hemorrhagic adenomas than in non-hemorrhagic ones." (PMID 30733705, 2019). "Hemorrhagic pituitary adenomas displayed higher protein and mRNA levels of TNF-α, vascular endothelial growth factor (VEGF) and matrix metalloproteinase-9 (MMP-9) compared with those of non-hemorrhagic tumors." (PMID 21747731, 2011).
bronchiectasis (20 papers, 2008 to 2025). Segmental, irreversible dilation of the bronchial tree resulting in the accumulation of secretions which leads to obstruction. "Serum SIRT-1 and MMP-9 levels were compared between healthy individuals and bronchiectasis patients, and the diagnostic sensitivity of these tests was assessed." (PMID 40290232, 2025). "Since it has been proven that SIRT-1 can affect inflammatory pathways by inhibiting NF-κB activity, it can be concluded that decreased SIRT-1 activity and high MMP-9 levels are associated with increased inflammatory conditions in bronchiectasis patients." (PMID 40290232, 2025). "Elevated levels of matrix metalloprotease 9 (MMP-9) and neutrophil elastase (NE) are associated with bronchiectasis and lung function decline in patients with cystic fibrosis." (PMID 36362203, 2022). "Guan and colleagues reported increased levels of MMP-8, MMP-9 and MMP-9/TIMP-1 ratio in patients with bronchiectasis and found an association between those levels and both disease and radiological severity." (PMID 34206113, 2021). "Taking into account the levels in the control and patient groups, we concluded that elevated inflammation, which is anticipated to occur in bronchiectasis, may cause MMP-9 levels to increase and SIRT-1 levels to decrease." (PMID 40290232, 2025). "In addition, MMP-9 is implicated in many chronic lung pathologies, including bronchiectasis and cystic fibrosis." (PMID 29892293, 2018). "This study’s primary merit lies in its contribution to the sparse literature by comparing blood SIRT-1 and MMP-9 levels between bronchiectasis patients and healthy controls." (PMID 40290232, 2025). "MMP-8 and MMP-9 are significantly increased in patients with bronchiectasis compared with healthy controls and significantly increased during bronchiectasis exacerbations." (PMID 40174958, 2025). "Taken together, these approaches lend evidence to MMP-9’s involvement as a crucial mediator in bronchiectasis." (PMID 40290232, 2025). "A study of BALF from children with CF enrolled in the AREST CF study showed that MMP-9 activation increased with free NE and that MMP-9/TIMP-1 ratios strongly correlated with bronchiectasis progression in the preceding year." (PMID 40141278, 2025). "This work provides crucial information to illustrate the possible roles of these biomarkers in the pathophysiology of the illness by comparing the serum SIRT-1 and MMP-9 levels in bronchiectasis patients with those in healthy persons." (PMID 40290232, 2025). "This has been demonstrated by the presence of secretory leukocyte peptidase inhibitor (SLPI) cleavage fragments in lower airway secretions of patients with bronchiectasis with high MMP-9 and NE levels." (PMID 40174958, 2025). "We found that MMP-9 levels were significantly increased in the serum of patients with bronchiectasis, and this result strengthens the findings of the reports cited here." (PMID 40290232, 2025). "In certain areas, more research is required, even if this work is a valuable beginning point for comprehending the possible involvement of SIRT-1 and MMP-9 in the pathophysiology of bronchiectasis." (PMID 40290232, 2025). "Evidence suggests that some MMPs, including MMP-9, are involved in the pathophysiology of bronchiectasis." (PMID 40174958, 2025). "A statistically significant cut-off value for the diagnosis of bronchiectasis was obtained, according the ROC analysis of MMP-9 (Table-III)." (PMID 40290232, 2025). "In a study by Goeminneet al., compared with healthy controls, patients with bronchiectasis were reported to have higher sputum neutrophil and NE levels, as well as increased MMP-9 levels, when chronic P. aeruginosa infection was detected." (PMID 40174958, 2025). "MMP-8 and MMP-9 levels were also significantly higher in patients with bronchiectasis than in healthy controls and were strongly correlated with the progression of bronchiectasis." (PMID 36902466, 2023).